BARD1 (BRCA1 associated RING domain 1)
Diseases named in the same sentence as BARD1 in open-access papers (continued):
Sharing a sentence is not in itself a finding about the gene and the disease.
breast cancer (continued). "Nonetheless, there is multiple instances, listed in the evidence above, that the PVs of BARD1 not only increase the risk of breast cancer in general, but primarily of TNBC, and can be associated with age at first diagnosis of equal or under 50 years." (PMID 33114377, 2020). "The Bard1‐deficient, orthotopic model of breast cancer metastasis will be a useful preclinical model for translational studies." (PMID 32730698, 2020). "Deleterious BARD1 germline variants are significantly associated with early-onset breast cancer, according to recent studies." (PMID 32733558, 2020). "BARD1 isoforms are aberrantly expressed in various cancers, including breast cancer, and they are associated with poor prognosis." (PMID 32722046, 2020). "Over the last two decades, numerous BARD1 mutations/pathogenic variants (PVs) have been found in patients with breast cancer (BC) and ovarian cancer (OC)." (PMID 32679805, 2020). "On the grounds of these data, intensified breast cancer screening programs should be offered to women carrying pathogenic BARD1 gene variants." (PMID 32733558, 2020). "The BARD1 gene can significantly extend the monitoring options in patients at risk of breast cancer and during post-treatment follow-up." (PMID 33114377, 2020). "For example, women with the missense mutation C557S, just before the BRCT1 domain of BARD1, have an increased susceptibility to breast cancer." (PMID 32708251, 2020). "The assessment of efficacy of PARPi in breast cancer patients with the relatively frequent LoF mutations of BARD1 would be of necessity to improve patients’ outcomes." (PMID 33114377, 2020). "Our work is focused on the one of these genes, BRCA1-associated RING domain protein 1 (BARD1), and its oncogenic role in breast cancer." (PMID 33114377, 2020). "Sequencing analyses revealed that potentially pathogenic BARD1 variants likely conferred a low–moderate risk to hereditary breast cancer, but this association is inconsistent." (PMID 32726901, 2020). "The BARD1 protein also seems to be an interesting starting point in analyzing the causes of drug resistance in breast cancer cases." (PMID 33114377, 2020). "Although the effect of PARP inhibition on muscles remains elusive in the context of breast cancer, the Bard1‐deficient, orthotopic model will provide new opportunities to address this important question." (PMID 32730698, 2020). "BARD1 is a breast cancer susceptibility gene encoding a protein that primarily interacts with BRCA1 in DNA repair." (PMID 30925164, 2019). "Some breast cancer-related BRCA1 missense mutations disturb the function of the BRCA1/BARD1 complex." (PMID 30975222, 2019). "Case–control analyses have shown BARD1 loss of function variants to be associated with a low (< 2-fold) to moderate (> 2-fold) increase in risk of breast cancer and up to five-fold increase in risk of triple negative breast cancer." (PMID 31803232, 2019). "Many of the BARD1 variants tested have been recorded on ClinVar as having been isolated from patients with breast cancer or hereditary cancer-predisposing syndromes." (PMID 30925164, 2019). "While the role of the BRCA1 gene (MIM *113705) in breast cancer (BC) and ovarian cancer (OC) predisposition is well established, the role of BARD1 (MIM *601593) in BC/OC predisposition remains elusive." (PMID 31036035, 2019). "In a previous study, missense BARD1 variant, Cys557Ser (rs28997576), has been revealed to be highly upregulated in breast cancer families." (PMID 30975222, 2019). "In this study, we show that tamoxifen-resistant breast cancer cells are resistant to DNA-damaging chemotherapy because of upregulated BARD1 and BRCA1, which is caused by activated PI3K/AKT pathway." (PMID 29686231, 2018). "Both BRCA1 and BARD1 are known to be tumor suppressor genes, whose mutations are associated with an increased risk of breast cancer." (PMID 29686231, 2018).
breast cancer (continued). "In the proposed breast cancer gene group, mutations in BARD1 were found significantly more frequently in individuals with FBC than in ExAC controls (OR = 3.18, 95% CI 1.34–7.36, p = 0.012)." (PMID 28649662, 2017). "Only BARD1 mutations were significantly associated with an increased risk of breast cancer (OR = 3.18, 95% CI 1.34–7.36, p = 0.012) in case–control analysis." (PMID 28649662, 2017). "This is the first large study to show that BARD1 is a moderate risk breast cancer predisposition gene for FBC." (PMID 28649662, 2017). "KSR1 expression is positively associated with breast cancer 1, early onset (BRCA1), BRCA1-associated ring domain 1 (BARD1) and checkpoint kinase 1 (Chk1) levels in breast cancer specimens." (PMID 26425651, 2015). "BARD1 is a major binding protein of the breast cancer predisposition gene product BRCA1 and a tumor suppressor in its own right." (PMID 26415510, 2015). "A somatic mutation (Val695Leu) and a germline mutation in BARD1 associated with sporadic breast cancer (Val695Leu) and one (Gln564His) associated with ovarian cancer have been reported." (PMID 23056176, 2012). "An example in the case of breast cancer is the BARD1 Cys557Ser risk variant that rose in frequency in the easternmost county of Sudur-Mulasysla due to a population bottleneck in that region." (PMID 19503599, 2009). "Heterozygous pathogenic mutations in BARD1 were identified in 12 probands, resulting in a mutation frequency rates of 0.45% among high-risk breast cancer patients and 0.29% among ovarian cancer patients, while none of the BARD1 carrier had double heterozygous mutations." (PMID 40805222, 2025). "However, the histopathology of the breast cancers of the BARD1 mutation carriers and BRCA1/2 mutation carriers showed certain distinguishing characteristics." (PMID 40805222, 2025). "Mutation screening for BARD1 should be included in the test panel for breast cancer patients." (PMID 40805222, 2025). "Another study found an OR of 3.2 (p-value = 0.012; n = 2127) for breast cancer patients with a family history of breast cancer, while a large-scale case–control study indicated an OR of 2.3 (p-value = 0.04; n = 13,935), showing that BARD1 is associated with low to moderate risk for breast cancer." (PMID 40805222, 2025). "Although BARD1 mutations are rare, the findings suggest that testing for BARD1 should be included in breast cancer panels, and mutation carriers may need closer monitoring due to associated family cancer histories." (PMID 40805222, 2025). "While mutations of the BARD1 gene are classically associated with breast cancer, there are variants that may predispose patients to malignancy given the presumptive role in DNA repair." (PMID 40678160, 2025). "Moreover, a stronger association (OR = 5.4; p-value < 0.00001; n = 4469) between BARD1 PVs and familial breast cancer patients was reported." (PMID 40805222, 2025). "The risk was further enhanced (OR = 12.0; p-value < 0.00001; n = 782) for breast cancer patients who diagnosed under 40 years of age, suggesting that BARD1 may be a risk gene for early-onset familial breast cancer." (PMID 40805222, 2025). "However, BARD1 mutation carriers with bilateral breast cancer have been reported in Polish and Belarusian populations but not in Asian populations." (PMID 40805222, 2025). "Nonetheless, the inclusion of BARD1 in multigene panels for hereditary breast cancer testing remains justified, as BARD1 variants may contribute to cancer susceptibility, especially when considered in combination with other genetic or environmental factors." (PMID 41301857, 2025). "In this comprehensive analysis, ATRIP reached exome-wide significance for the first time, with protein-truncating variants conferring a statistically significant association with increased breast cancer risk, comparable in magnitude to other moderate-penetrance genes such as BARD1." (PMID 41440239, 2025).
breast cancer (continued). "Therefore, understanding the cancer risk and phenotypic presentations of BARD1 mutations in Chinese breast cancer patients can contribute to informed clinical management decisions." (PMID 40805222, 2025). "In a retrospective study of approximately 48,700 breast cancer cases and 20,800 ovarian cancer cases, BARD1 was identified as a moderate-risk gene for breast cancer (OR = 2.90, 95% CIs: 2.25–3.75, p-value < 0.0001) but not for ovarian cancer (OR = 1.36, 95% CIs: 0.87–2.11, p-value = 0.1733)." (PMID 40805222, 2025). "Similarly, in breast cancer, some studies have found that BARD1 polymorphisms were associated with a significantly decreased breast cancer risk; however, more research is needed to understand how SNP-altered gene expression patterns affect tumor behavior." (PMID 41009605, 2025). "Moreover, the prevalence and frequency of BARD1 mutations vary across different ethnic groups in breast cancer." (PMID 40805222, 2025). "Many studies have estimated the contribution of BARD1 mutations in breast cancer susceptibility." (PMID 39684352, 2024). "Therefore, mutations in BARD1 have been postulated to confer oncogenic functions and predispose patients to developing breast cancer." (PMID 39233942, 2024). "Deleterious germline variants in the BRCA1-associated ring domain (BARD1) gene moderately elevate breast cancer risk; however, their potential association with other neoplasms remains unclear." (PMID 38485918, 2024). "In addition, the genes that were tested in this study are not inclusive of all genes in which there are now data to support breast cancer risk association, including BARD1, RAD51C, and PTEN." (PMID 36544278, 2023). "BRCA1-associated ring domain (BARD1) gene deleterious germline variants are associated with a moderate increase in the relative risk of breast cancer, but their association with other neoplasms, such as CRC, remains unclear." (PMID 36709314, 2023). "Additionally, the study also highlights the role of BARD1 as an oncogene in breast cancer patients and its potential uses as a prognostic/diagnostic biomarker and as a therapeutic target for cancer susceptibility testing and treatment." (PMID 35650591, 2022). "Thus, highlighting the substantial involvement of breast cancer positive family history increased the risk of genetic predisposition to breast cancer, particularly in BARD1 polymorphism carriers." (PMID 35650591, 2022). "Collectively, while this BARD1 Cys557Ser mutation was reported to link to breast cancer incidence in Iceland, Finland, Spanish/South American, and Italy, other reports from Yoruba, Chinese, Japanese, Australian, and African-American individuals didn’t show similar findings." (PMID 35650591, 2022). "Likewise, in a large pooled analytical study of both breast cancer (48,000 cases) and ovarian cancer (20,800 cases), many pathogenic variants (PVs) of the BARD1 gene were cataloged." (PMID 35650591, 2022). "GPVs in BARD1 have been associated with early onset of breast cancer." (PMID 35008774, 2021). "The most commonly studied is the association between BARD1 and breast cancer." (PMID 34771627, 2021). "The association between breast cancer and mutations in the BARD1 gene was first found in a large case-control study of 65,057 women with breast cancer, where the prevalence of BARD1 mutations was 0.18%, significantly greater than the controls (OR = 2.16, 95% CI: 1.31-3.63, p < 0.05)." (PMID 33959510, 2021). "Therefore, the evidence of the association of BARD1 mutations with a genetic predisposition to cancers other than breast cancer is controversial." (PMID 34771627, 2021). "Breast cancer-derived BARD1 variants C645R, V695L, and S761N show decreased association with OLA1." (PMID 32722046, 2020). "Data on patients with BARD1 gene polymorphism undergoing NACT for breast cancer are limited." (PMID 33114377, 2020).
breast cancer (continued). "Thus, the Bard1‐deficient breast cancer metastasis model develops skeletal and cardiac muscle atrophy systemically affecting multiple muscle groups." (PMID 32730698, 2020). "In conclusion, BARD1 is likely to be a low–moderate penetrance breast cancer risk gene." (PMID 32726901, 2020). "Interestingly, the patient’s father also harbored the BARD1 germline mutation and had many relatives with early-onset breast cancer." (PMID 32708251, 2020). "Similarly, the BARD1 variants S241C and E361D, which have been found in patients with breast cancer and are benign according to ClinVar, are functional in HDR (blue dots)." (PMID 30925164, 2019). "However the results obtained from our case-control study in founder populations should be very helpful to corroborate the role of BARD1 as a breast cancer susceptibility gene." (PMID 31142030, 2019). "Furthermore, numerous studies of individuals who have a family history of breast cancer have found rare and functionally deleterious variants in BARD1." (PMID 31803232, 2019). "Indeed, two common exonic variants identified on BARD1 gene (rs2229571 and rs1048108) have been identified as low penetrant breast cancer loci in the Chinese population." (PMID 29879995, 2018). "The case-control association analysis between 38,326 white patients with breast cancer and 26,911 ExAC controls demonstrated an association between pathogenic rare variants in BARD1 with a moderate risk value (Odd Ratio, 2.16; 95% confidence interval: 1.31–3.63) and a mutation frequency of 0.18%." (PMID 29292755, 2017). "BRCA1 physically binds to BARD1, another protein that was linked to breast cancer susceptibility." (PMID 28506208, 2017). "However, many SNPs have been reported in BARD1 but only two have been suggested to be involved into breast cancer susceptibility." (PMID 23056176, 2012). "This supports the observation that SNPs of XPD (ERCC2), BARD1 and IL-10 may be good candidates for breast cancer predisposition, which may also modify the effect of BRCA1 in carriers." (PMID 16672066, 2006). "Thus, the BARD1 gene is a diagnostic biomarker in testing breast cancer patients." (PMID 35650591, 2022). "Furthermore, the BRCA1/BARD1 heterodimer interaction was disrupted by BARD1 or BRACA1 mutations associated with the presence of breast cancer, such as mutations of the RING finger domain, missense mutations, and alterations of ANK sequences that are involved in the regulation of transcription." (PMID 35650591, 2022). "Here we report the identification of DDB1 and CUL4-associated factor 8-like protein 1(DCAF8L1), a novel DCAF protein which is encoded by an X-linked gene, plays crucial role in targeting BRCA1/BARD1 for proteasomal degradation, and might be involved in the development of breast cancer." (PMID 35280675, 2022). "However, a female relative of a man with a BARD1 mutation may benefit from this information and she may be tested for this mutation, because BARD1 is a breast cancer susceptibility gene." (PMID 34771627, 2021). "However, a female relative of a man with a BARD1 mutation may benefit from this information and be tested for the mutation, because BARD1 is a breast cancer susceptibility gene." (PMID 34771627, 2021). "However, a female relative of a man with a BARD1 mutation may benefit from this information and be tested, because BARD1 is a breast cancer susceptibility gene." (PMID 34771627, 2021). "Injection of Bard1‐deficient tumor cells into the mammary fat pad of syngeneic mice led to spontaneous lung metastasis and gradual cachexia development, generating a useful resource for analyzing the mechanisms that underlie both metastatic progression and muscle wasting in breast cancer." (PMID 32730698, 2020). "Furthermore, breast cancer cells that were treated with adipocyte-conditioned media upregulated proliferation and metastasis while also downregulating BRCA1-associated RING domain protein 1 (BARD1), a tumor suppressor, and p18, a cell-cycle checkpoint inhibitor." (PMID 30717356, 2019).
breast cancer (continued). "However,other genes, such as ATM, PALB2, BRIP1, CHEK, BARD1, while lower in frequency, may also increase breast cancer risk." (PMID 29093764, 2017). "Beyond the high-penetrance genes associated with breast cancer, moderate-risk genes, such as ATM, BARD1, and CHEK2, also contribute to hereditary breast cancer predisposition and are therefore considered part of the HBOC spectrum." (PMID 41528496, 2026). "In our Asian cohort, the prevalence rates of PVs in BARD1 in the breast cancer group (0.45%) and the ovarian cancer group (0.29%) were significantly higher than the reported mutation frequencies." (PMID 40805222, 2025). "BARD1 PVs in breast cancer patients of European ancestry had an odds ratio (OR) of 2.2 (p-value = 0.002; n = 28,536)." (PMID 40805222, 2025). "The nonsense PV BARD1:c.2229dup p.(Asn744Ter) was detected in four unrelated patients with breast cancer." (PMID 40065011, 2025). "Tamoxifen-resistant breast cancer cells exhibit significantly elevated levels of BARD1 and BRCA1, contributing to their resistance to DNA-damaging chemotherapy." (PMID 39858015, 2025). "The Breast Cancer Association Consortium and the CARRIERS case-control studies also found associations between PV in the BARD1 gene and an increased risk of developing triple-negative breast cancer, something we had also reported in our patients." (PMID 40508121, 2025). "Another Asian study from Singapore also found that patients with BARD1 PVs developed more aggressive triple-negative breast cancer and high-grade breast cancers." (PMID 40805222, 2025). "Most breast cancer susceptibility genes are involved in the damage repair signaling pathway, i.e., including BRCA1, BRCA2, PALB2, CHEK2, ATM, BARD1, RAD51C, and RAD51D." (PMID 40649769, 2025). "BARD1 carriers favor the development of high-grade invasion breast cancer, the same as BRCA1 carriers (p-value = 0.204), while BRCA2 carriers and non-carriers develops less aggressive tumors (p-values = 0.004 and <0.001 respectively)." (PMID 40805222, 2025). "Individuals with BARD1 and BRCA1 germline pathogenic mutations have been found to have a higher incidence rates of aggressive breast cancer phenotypes, such as TNBCs, which are associated with higher rates of recurrence, progression, and mortality." (PMID 40805222, 2025). "The Breast Cancer Association Consortium and the CARRIERS case–control studies also found associations between BARD1 PVs and an increased risk of triple-negative breast cancer." (PMID 40805222, 2025). "BOADICEA V5’s newest version includes the effects of pathogenic variants (PVs), not restricted to BRCA1 and BRCA2 genes but also in PALB2, CHEK2, ATM, and BARD1 for the breast cancer model and RAD51D, RAD51C, and BRIP1 for the ovarian cancer model." (PMID 39590369, 2024). "Other homologous recombination DNA damage repair (HR-DDR) genes associated with breast cancer risk accounted for 15.9% (13/82) of the carriers, including ATM (n = 2), BARD1 (n = 4), CHEK2 (n = 1), PALB2 (n = 2), RAD51C (n = 1), and RAD51D (n = 3)." (PMID 38893140, 2024). "While BRCA1 and BRCA2 remain the most well-known high-penetrance genes, others, such as ATM, BARD1, CHEK2, PALB2, RAD51C, and RAD51D, are now recognized as conferring moderate to high risk for breast cancer." (PMID 39590369, 2024). "Analogous to breast cancer patients with BRCA1 mutations, mice bearing Brca1- and Bard1-deficient tumors display remarkable initial responses to PARPi that are inevitably followed by disease progression." (PMID 38956205, 2024).